ANGPT2 (angiopoietin 2)
Diseases named in the same sentence as ANGPT2 in open-access papers (continued):
Sharing a sentence is not in itself a finding about the gene and the disease.
tumor (continued). "As EC‐secreted Angpt2 promotes angiogenesis, we investigated whether Angpt2 secreted by tumor cells retains this function by using zebrafish embryos xenografts, an established model to study angiogenesis in vivo." (PMID 35266635, 2022). "In addition, we observed a significant correlation between levels of CCL4 and Angpt2 expression in tumor specimens." (PMID 35884919, 2022). "Therefore, the high ANGPT2 expression can activate a variety of tumor-related pathways and immune responses, suggesting that ANGPT2 plays a significant role in the occurrence and development of GC." (PMID 36172371, 2022). "Rarely, co‐expression of ANGPT1 and ANGPT2 was observed in few tumor cells." (PMID 35266635, 2022). "Importantly, encouraging results have recently shown that ANGPT2 inhibition restored vascular stability, repressed tumor angiogenesis, and decreased the metastatic burden and proportion of sorafenib tolerance of early or even advanced-stage malignancies." (PMID 35987690, 2022). "To verify whether tumor‐bound Tie2 can interact with Angpt2, as it occurs for EC‐bound Tie2, we employed proximity ligation assay (PLA) on rat NF‐PitNET tissues using antibodies against Angpt2 and Tie2." (PMID 35266635, 2022). "Thus, Angpt2 joins the array of growth factors and cytokines that tumor cells release to regulate angiogenesis, foster EC survival and ultimately promote progression." (PMID 35266635, 2022). "Thus, therapy-induced upregulation of ANGPT2 potentially drives tumour resistance to VEGFR2 blockade." (PMID 35513564, 2022). "ANGPT2 plays a key role in tumor angiogenesis, tumor inflammation, and tumor metastasis." (PMID 36172371, 2022). "In murine subcutaneous tumor tissues, ANGPT2 expression of DNAse-1-treated mice was significantly decreased, which proved that inhibition of NETs could significantly reduce ANGPT2 expression." (PMID 36172371, 2022). "To prove that Angpt2 secreted by tumor cells is bioactive, we assessed cell proliferation by exposure of scRNA‐ (control) or siAngpt2‐transfected GH3 cells (to suppress endogenous Angpt2 secretion) to the serum‐free CM of primary rat NF‐PitNET cells, which predominantly express Angpt2 (Fig EV1)." (PMID 35266635, 2022). "We demonstrate that CCL4 promotes Angpt2 expression in OSCC by activating signal transducer and activator of transcription 3 (STAT3) and mitogen-activated protein kinase kinase (MEK), signal-regulated kinase 1/2 (ERK) signaling, which subsequently enhances Angpt2-induced tumor angiogenesis." (PMID 35884919, 2022). "In the tumor microenvironment, mesenchymal stem cells can secret ANGPT2." (PMID 36569220, 2022). "Of note, the serum‐free CM of rat NF‐PitNET cells promoted the viability of isolated rat primary ECs (+20%; P = 0.036; Fig EV2) indicating that tumor‐borne angiopoietins (in NF‐PitNETs primarily Angpt2) might work as cytokines on ECs within the tumor TME." (PMID 35266635, 2022). "The number and size of the tumor, like in the Milan criteria or Metroticket, are clearly insufficient for prognostication and only the addition of angiopoietin-2 for Milan criteria, or AFP for Metroticket, makes them able to discriminate between low and high risk of the event." (PMID 36158651, 2022). "Numerous studies have demonstrated that ANGPT2 mostly explored in tumor-induced angiogenesis, where its overexpression or inhibition increased or decreased the angiogenesis capability, respectively, suggesting a critical role for ANGPT2 in angiogenesis." (PMID 35987690, 2022). "Our results suggest that biglycan destabilizes tumor blood vessels by mediating Angpt2 expression." (PMID 33966638, 2021). "VEGF and the growth factor angiopoietin-2 participate in this process by inhibiting the proliferation and differentiation of the activated immune effector cells while at the same time recruiting suppressive tumor-related immune cells." (PMID 34778292, 2021).
tumor (continued). "Although angiogenic growth factors such as Angiopoietin 2 (Ang2) play a central role in tumor angiogenesis in HCC, the role of serum Ang2 as a biomarker in HCC remains unclear." (PMID 33854629, 2021). "MiR-100 reduces the protein level of angiopoietin 2 (Angpt2) by targeting mTOR and blocking the mTOR-p70S6K signaling pathway, which in turn inhibits the formation of encapsulated tumor clusters (VETC), thereby eliminating VETC-dependent metastasis of HCC cells." (PMID 34123955, 2021). "Clinical studies have proven that high levels of Angiopoietin-2 indicate the development of non-small-cell lung carcinomas (NSCLC), while high levels of Angiopoietin-2 are strongly related to tumor angiogenesis, lymphangiogenesis, metastasis, and poor prognosis." (PMID 34833409, 2021). "Currently, ANGPT2 has been playing an important role in tumor angiogenesis and might confer resistance to sorafenib therapy." (PMID 34178637, 2021). "We next confirmed that Angpt2 mRNA expression was decreased in tumor tissues from Bgn KO mice." (PMID 33966638, 2021). "Besides, an experimental study demonstrated the distinct expressions of angiopoietin-1 and angiopoietin-2 in tumor samples of human oral SCC." (PMID 32799882, 2020). "ANGPT2, as a member of the secretion cytokine family, was active in several important biological processes, including vascular remodeling, wound repair, and tumor angiogenesis." (PMID 32908897, 2020). "In addition, tumor endothelium-released angiopoietin-2 (TIE-2) was reported to play an significant role in tumor angiogenesis by recruiting monocytes that express the TIE-2 receptor." (PMID 33251232, 2020). "In conclusion, ANGPT2 might serve as a potential predictive biomarker for ICIs and a possible target for combinations that could help reduce myeloid cell infiltration and tumor immunosuppression." (PMID 32793228, 2020). "Furthermore, ANGPT2 negatively influences tumor immunity by recruiting M2-like TAMs and Tie-2-expressing monocytes/macrophages (TEMs) into tumors; TEMs then promote Treg infiltration via IL-10 but suppress CTL activation." (PMID 32913278, 2020). "Each TMEM doorway is composed of one proangiogenic CD206 macrophage expressing high levels of Tie2 receptor, one tumor cell expressing high levels of actin regulatory protein Mena, and one endothelial cell expressing angiopoietin-2 (Ang2), all in direct physical contact." (PMID 32714862, 2020). "This study indicates that HCC cell-secreted exosomal ANGPT2 has a novel pathway to induce tumor angiogenesis that is different from the classic ANGPT2/Tie2 pathway of free ANGPT2; targeting this way may improve current antiangiogenic therapies." (PMID 32183816, 2020). "On the other hand, the RAGE-positive peri-tumoral ductular cells could possibly communicate with hepatocytes via cytokines such as angiogenic factors ANGPT2 and PDGFβ to promote angiogenesis tumor development." (PMID 32382012, 2020). "We propose that rs12674822 may increase Angpt2 mRNA expression by affecting tumor-derived endothelial cell apoptosis in CRC." (PMID 31929743, 2020). "However, the ANGPT2 protein abundance was higher in tumor with big size (T3-T4) than that in small size (T1-T2) (P=0.0417)." (PMID 31892982, 2020). "CTGF enhances ANGPT2 expression, a key element in tumor angiogenesis." (PMID 31285444, 2019). "In mouse tumor transplantation studies, exogenous Angpt4 has been reported to either inhibit or promote tumor growth, and similarly to Angpt2, Angpt4 expression has been reported to increase in hypoxia." (PMID 30444491, 2018). "The secretion of ANGPT2 by tumour cells has been proposed to induce chemotaxis of TIE2+ monocytes." (PMID 29367702, 2018). "In addition, antibody-mediated neutralisation of angiopoietin 2, the ligand for the Tie2 receptor, or macrophage depletion blocks tumour angiogenesis and limits tumour progression in a mouse model of breast cancer." (PMID 28210073, 2017).
tumor (continued). "It has also been revealed that blocking of ANGPT2 protein may induce vascular normalization in tumors, inhibit transendothelial migration of tumor cells, and decrease pulmonary metastasis and growth of experimental tumors." (PMID 29017512, 2017). "Moreover, tumor endothelial cells express elevated ANGPT2 levels, and this correlates with tumor angiogenesis and poor prognosis in many cancers." (PMID 29118335, 2017). "Interestingly, host cell expressions of several markers were strongly upregulated towards the tumour bulk, but hardly visible outside the tumour region, including Vimentin and the angiogenic factors Angiopoietin 2, VEGF and FGF2." (PMID 28173797, 2017). "In addition, angiopoietin-2 can stimulate tumor cell metastasis to lymph nodes and lung, via activating tumor cell ITGB1." (PMID 27353038, 2016). "Since there is no Ang2-responsive ECs in mesenchymal niche, we hypothesized that angiopoietin-2 may act on tumor cells directly." (PMID 27353038, 2016). "Knockdown of ANGPT2 completely negated ER+ tumor cell awakening in the niche." (PMID 27353038, 2016). "Then, tumor cell proliferation rates upon ANGPT2 knockdown in niche were examined." (PMID 27353038, 2016). "After 72 h, all three ER+ tumor cells in estrogen-deficient endothelial niche did not proliferate when ANGPT2 was knocked down." (PMID 27353038, 2016). "Increased angiopoietin-2 in estrogen-depleted endothelial niche may have shifted tumor cell behavior from dormancy to awakening." (PMID 27353038, 2016). "Our results underscore the direct action of angiopoietin-2 on ER+ tumor cells too." (PMID 27353038, 2016). "In addition, it is also known that angiopoietin-2 (Ang-2), a cytokine upregulated in tumor endothelial cells and some tumor cells including NSCLC, stimulates tumor angiogenesis in collaboration with VEGF and other proangiogenic factors." (PMID 27589869, 2016). "Angiopoietin-2 (ANG-2) is known to differentially regulate the tumor angiogenesis." (PMID 27561007, 2016). "In primary organ, ANGPT2 directly stimulates tumor angiogenesis." (PMID 27353038, 2016). "ANGPT2 overexpression has also been shown to augment tumor angiogenesis." (PMID 25885592, 2015). "However, as well as CCL2, ANGPT2 has been demonstrated to promote tumor growth indirectly via increase of TIE2+ TAM-like macrophages in the tumor microenvironment." (PMID 25883937, 2015). "This was further emphasized by mRNA analysis of whole tumor preparations, where a significant elevation in hypoxia-related genes (i.e. Glut-1 (Slc2a1), Angpt2, Stc2, and Semaphorin B) could be seen coinciding with reduced CD31-staining." (PMID 26673090, 2015). "In addition, ANGPT2 plays a significant role during early stages of the angiogenic switch in the formation of tumours when it induces apoptosis in endothelial cells; this results in massive hypoxia in the concerned tumour tissue." (PMID 26044849, 2015). "There was a significant correlation between ANGPT2 levels and tumor size (p = 0.0009)." (PMID 25885592, 2015). "Therefore, an increased expression of ANGPT1 and ANGPT2 in tumour tissue hints to an escalation of tumour malignancy on the grounds of an altered vascularisation." (PMID 26044849, 2015). "Angiopoietin-2 (Angpt-2) has been employed as a biomarker of angiogenesis and might be involved in tumor neoangiogenesis." (PMID 24823366, 2014). "Moreover, Dkk-3 and ANGPT2 were inversely regulated in human umbilical vein endothelial cells after knockdown of Axl 36, suggesting a role of Dkk-3 in tumor angiogenesis." (PMID 23765731, 2013). "Alteration of cEPCs and angiopoietin-2 by rhTNF-α might account for the cytotoxicity and hemorrhagic effects on tumor vessels during limb perfusion procedures." (PMID 22948772, 2013). "ANGPT2 is emerging as a key regulator of vascular remodeling during tumor angiogenesis." (PMID 21347233, 2011).
tumor (continued). "Angiopoietin-2 has been implicated in promoting vascular remodeling and tumor adaptation to hypoxia, suggesting that its transient increase post-TACE may contribute to tumor progression." (PMID 40867270, 2025). "Furthermore, our results indicate that ANGPT2 blockade may not only make tumor blood vessels more permissive to T cell infiltration, but also enhance T cell activation." (PMID 37843277, 2023). "However, the contribution of ANGPT2-mediated vascular destabilization to tumor immune escape in metastatic disease remains unclear." (PMID 37843277, 2023). "However, using immune-deficient mice, the underlying mechanism of reduced tumour volume and vessel numbers due to AA treatment, might be rather the changed secretome by the tumour cells, including inhibition of ANGPT2 secretion by AA." (PMID 35513564, 2022). "Therefore, it also proves that ANGPT2 participates in tumor immune response and targeting neutrophil/NETs-ANGPT2 may be a new target of anti-tumor therapy in the future." (PMID 36172371, 2022). "Furthermore, the in vivo results showed that silencing ANGPT2 significantly reduced the fluorescence intensity in MYBL1-overexpression tumor cells and downregulation of ANGPT2 dramatically reduced the number of CD31-positive microvessels in MYBL1 transfected mice." (PMID 35987690, 2022). "Furthermore, macrophage infiltration into human glioblastomas, resistant to anti-VEGF therapy, is correlated with a poor prognosis, but a combinatorial therapy with anti-VEGF and anti-ANG2 (angiopoietin-2) was shown to reprogram TAMs from M2 into M1 phenotype with relevant anti-tumor activity." (PMID 35664746, 2022). "Thus, it is suggested that ANGPT2 may be one key factor that promotes tumour neo-angiogenesis and being downregulated by AA in vivo and in vitro." (PMID 35513564, 2022). "C57 cells caused approximately 60% reduction of tumor volume by inhibiting tumor vascularization as indicated by modified blood vessel morphology and downregulation of proangiogenic factors, including VEGF, placental growth factor, and angiopoietin-2, and inducing apoptosis." (PMID 34393784, 2021). "Besides, we also evaluated ANGPT2 levels in GC and non-tumor adjacent tissue by RT-PCR and IHC." (PMID 33758610, 2021). "In our study, the increased angiopoietin 2 in plasma after surgery suggests that surgical injury may trigger the release of proangiogenic factors and facilitate the proliferation and metastasis of residual tumor cells in HNSCC." (PMID 32799882, 2020). "Additionally, both VEGFA and ANGPT2 protein levels were significantly associated with the tumor size and lymph node metastasis only in ADC, not SQC." (PMID 31892982, 2020). "The expression of ANGPT2 in tumor-derived exosomes remains unknown." (PMID 32183816, 2020). "In addition, angiopoietin-2 (ANG-2) is able to recruit circulating Tie2-expressing monocytes (TEMs) that inhibit apoptosis in both tumor and endothelial cells, by mechanisms depending on TNFα release, and exhibits an essential pro-angiogenetic role with a not completely clarified mechanism." (PMID 31447834, 2019). "Pro-angiogenic growth factors secreted by tumor cells, such as angiopoietin-2, epidermal growth factors (EGFs), fibroblast growth factors (FGFs), vascular endothelial growth factors (VEGFs), and platelet-derived growth factors (PDGFs) can stimulate angiogenesis around tumor tissue." (PMID 29086859, 2017). "In conclusion, we demonstrate that ANGPT2 signaling activated after estrogen depletion paradoxically triggers ER+ tumor cell awakening from dormancy in their BM niche, partly indirectly via endothelial Tie2 receptor and partly directly via tumor cell surface integrin &1." (PMID 27353038, 2016). "Systemic angiopoietin-2 levels may be used as an alarm of disseminated tumor cell awakening too." (PMID 27353038, 2016).
tumor (continued). "Moreover, the discovered findings are in keeping with a hypothesis that in the presence of VEGF, angiopoietin-2 may collaborate at the front of invading vascular sprouts, serving as an initial angiogenic signal that accompanies tumor growth." (PMID 29147212, 2010). "RNA-seq analysis confirmed that, after ANGPT2 knockout, the expression scores of key genes involved in EMT, tumor metastasis, proliferation, and hypoxia-related pathways were markedly reduced in the PC12 cell line." (PMID 41400463, 2025). "In parallel, they overexpressed pro-angiogenic markers such as ANGPT2 and PKM2, suggesting tumor hyper-vascularization, which is the primary target of the anti-angiogenic agent sorafenib." (PMID 40332478, 2025). "We selected CXCR7, angiopoietin 2, and ANTXR1 (also known as tumor endothelial marker 8, TEM 8), as putative markers of TEC." (PMID 40348600, 2025). "Angiogenesis, crucial for tumor growth, is heightened in CTCL, as it is supported by elevated levels of CXCL12-CXCR4 and Ang2-Tie (Angiopoietin 2-tyrosine kinase receptor) signaling during MF and SS, respectively, facilitating EC activation." (PMID 40055269, 2025). "Tumor angiogenesis occurs through the action of many angiogenic factors, which usually also participate in physiological angiogenesis, such as HIF-1α and angiopoietin-2 (ANG-2)." (PMID 40429943, 2025). "We also observed ECs with increased angiogenic activity driven by tumor-mediated VEGF-VEGFR activated pathway network involving PVLAP and ANGPT2 in the endothelium with a concomitant reduction in immune activity during non-solid to solid disease progression." (PMID 39803458, 2025). "Depleting both monocyte-derived and lung-resident TAMs enhanced tumor response to “antiangiogenic immunotherapy” (a combination of VEGFA, angiopoietin-2, and PD1 blockade) in NSCLC models." (PMID 40475851, 2025). "In contrast, CUX1 and ANGPT2 were upregulated in metastatic fibroblasts, and SP3 was upregulated in metastatic tumor cells relative to their expression in the primary tumor." (PMID 40095604, 2025). "To this aim, we administered A2V (a bispecific antibody against angiopoietin-2 and VEGFA44) and PD1 antibodies, or irrelevant IgGs, to mice 15 days post-tumor inoculation, and examined lung tumor growth at day 28 using micro-CT imaging." (PMID 40475851, 2025). "This study represents the first demonstration that PD-L1 blockade therapy inhibits tumor angiogenesis and normalizes tumor vessels via IFN-γ-mediated suppression of ANGPT2 and Tie2." (PMID 40370455, 2025). "In transgenic and transplanted tumour models, the blockade of VEGF‐A and ANGPT2 by bispecific antibody (A2V) significantly enhances antitumour immunity and promotes the accumulation of CD8+ CTLs." (PMID 40268524, 2025). "ANGPT2 and Tie2 are predominantly expressed in ECs, whereas VEGF-A is primarily expressed in tumor cells." (PMID 40370455, 2025). "Factors secreted by ECs, including VEGF, matrix metalloproteinases (MMPs) and angiopoietin-2 (Ang-2), have been shown to promote angiogenesis and EMT in various cancer types, facilitating tumor cell invasion and metastasis." (PMID 39944338, 2025). "Our results uncovered the predominant expression of ANGPT2 and TEK in HUVECs and HPMECs, whereas VEGF-A was expressed primarily in tumor cells." (PMID 40370455, 2025). "Given that IFN-γ is a widely distributed cytokine produced in response to anti-PD-L1 therapy, we validated its capability to inhibit the expression of ANGPT2 and Tie2 in ECs and reduce the expression of VEGF-A in tumor cells." (PMID 40370455, 2025). "In summary, this study reveals differential activation of salvage angiogenic pathways in surgical specimens, with FGF2, EphA2, and PLGF upregulated in tumor vessels, while ANGPT1 and ANGPT2 were downregulated and upregulated, respectively." (PMID 38619734, 2024). "Dual angiopoietin-2 (Ang-2) and VEGF blockade induce a higher expression of VCAM-1 on tumor endothelial cells, allowing the accumulation of antitumor T cells." (PMID 39325128, 2024).